IL7R (interleukin 7 receptor)
Diseases named in the same sentence as IL7R in open-access papers (continued):
Sharing a sentence is not in itself a finding about the gene and the disease.
infection (continued). "In the absence of T and B cells, there were fewer analytes altered with infection or with anti-IL-7Rα M595 treatment compared with the number of changes seen in Hb-infected Mdr1a−/− mice." (PMID 23057802, 2012). "The expression of IL-7Rα on each subtype was determined, and numbers of total or IL-7Rα+ pDC, mDC, NK, Mac2, and Mac3 cells were increased with Hb infection." (PMID 23057802, 2012). "Among these markers, IL-7Rα (CD127) which is down-regulated on most of the effector cells early after infection, but the proportion of cells expressing CD127 increases as the response contracts." (PMID 23346085, 2012). "As both CD4 and CD8 IL-7Rα449F T cells showed a dose dependent defect in anti-CD3 induced division, we postulate the route of infection and antigenicity of pathogen challenge can determine the requirement for IL-7R signals." (PMID 23189186, 2012). "Circulating concentrations of lymphotactin, MIP-1γ, MPO, MMP9, as well as VCAM-1, CRP, SAP, and haptoglobin were altered with Hb-infection and reduced in Hb-infected mice treated with anti-IL-7Rα M595." (PMID 23057802, 2012). "In this work, we showed that C. albicans invasive infection with a low virulence strain results in a rapid expansion of HSPCs (identified as LKS cells: Lin− c-Kit+ Sca-1+ IL-7Rα−), that reach the maximum at day 3 post-infection." (PMID 21935459, 2011). "For instance, the persistent expression of IL7R is a cardinal feature of naïve and memory CD8+ T cells, but IL7R is only expressed by a small fraction of effector CD8+ T cells during acute LCMV-Arm+ infection, consistent with the accessibility profile at the Il7r locus." (PMID 39804040, 2025). "IL-7R may be useful for predicting the number of memory T cells generated after infection or immunization." (PMID 41614877, 2025). "We found that the frequency of NP+CD8+ T cells in the lung and spleen was similar between Brd7fl/fl mice and Brd7ΔT mice, while a reduction of antigen-specific KLRG1+IL-7R– SLECs was found in the Brd7ΔT mice after infection with HKx31 viruses of previously PR8-primed mice." (PMID 38954484, 2024). "Similarly, the percentage of IE-1, pp65, and gB-specific CD8+ T cells expressing IL-7R+ was higher in control subjects with remote infection than in pregnant women with HCMV primary infection at the early and late time points." (PMID 39336935, 2024). "Despite the sparsity of the observed substantial differences in signatures of CXCR4- and CCR5-tropic latency, we have noticed that among genes identified in our dataset, the interleukin 7 receptor (IL7R) was upregulated in latently infected cells for CCR5-tropic infection only." (PMID 38156317, 2023). "The observed lower expression of T cell associated genes (e.g. IL7R, CD3E, CCR7 and PTPRCv1) in TB patients has been shown previously and might be associated with reactivation of infection and migration of cells to the site of infection." (PMID 31821366, 2019). "In Listeria monocytogenes-infected mice, the adoptive transfer of cells expressing high amounts of IL-7R α-chain (CD127) helped to control infection due to the expansion of effector cell populations responsible for the rapid clearance of bacteria from the spleen and liver." (PMID 25569149, 2015). "TCF-7 and IL-7R were downregulated whatever the cause of CRD and this could play a role in the higher susceptibility to infection of these patients." (PMID 25329529, 2014). "The decrease in these two cytokines with infection and increase with anti-IL-7Rα treatment may be due to homeostatic regulation." (PMID 23057802, 2012). "Costimulatory molecules (CD80, CD86, CD40, GITR, and ICOS), adhesion molecules (VCAM-1 and P-selectin), and signaling molecules involved in cytokine regulation (Tbx21 and Socs1) were also increased with Hb infection and decreased with anti-IL-7Rα M595 treatment in a dose-dependent manner." (PMID 23057802, 2012).
infection (continued). "However the effect of both these cytokines on Bcl-2 and IL-7Rα expression in CD8+ T cells during acute phase of infection remains understudied." (PMID 20520779, 2010). "Interestingly, patients with acute infection who subsequently resolved the infection had higher baseline values of IL-7Rα expression (i.e. at time of acute infection) than patients with acute infection who subsequently evolved toward chronic infection." (PMID 21994550, 2009). "Similarly, IL-7R internalization triggered by IL-7 stimulation may explain the reduced CD127 expression characterizing circulating HIV-specific CTLs during hyperacute infection in patients." (PMID 28579989, 2017). "Secondly, increased soluble IL-7R has been shown to bind free IL-7 and to inhibit IL-7 signaling (and therefore immune effector functions) in CD8+ T-cells from patients with infections; inhibition of IL-7, via binding to soluble IL-7R, could potentially impact on GVHD development." (PMID 24946690, 2014). "‘Neutralized’ IL-7, by binding to the sIL-7R may not accessible to IL-7R-positive immune cells; this situation may be associated with increased risk of infections." (PMID 24946690, 2014). "Transcription levels of the myeloid-associated genes C/EBPα, PU.1, FOG1, and G-CSF were increased in total BM cells by 2–3-fold at 12 h post infection, while transcription levels of the lymphoid-associated genes IL7-R, Flt3, Rag1, PAX5, and Ikaros did not change at this time point." (PMID 23189271, 2012). "Based on IL7R, GZMK, mir-93-5p, and mir-345-5p we suggest a novel possible workflow to distinguish infection, where those markers are downregulated, from rejection, where they are overexpressed, on EMB specimens." (PMID 40453097, 2025). "At day 14 p.i., we sorted CD45.1+CD45.2+CD44+Tigit+IL-7Rα–PD-1+CXCR5+ and CD45.1+CD44+Tigit–IL-7Rα+PD-1+CXCR5+ CD4+ T cells and co-transferred them into CD45.2+ recipient mice followed by PR8 infection." (PMID 37330549, 2023). "Greater numbers of virus-specific effector CD4+ and CD8+ T cells in Selplg-/- mice were found early after infection, and MPEC phenotype T cells with significantly elevated expression of IL-7R predominated by 8dpi." (PMID 34326837, 2021). "Interestingly, discrimination analysis identified a number of T cell-related genes (e.g., IL7R, LY9, and TCP1) that were uniquely upregulated with Makona-C07 infection, which may reflect aberrant T cell activation associated with fatal outcomes in EVD patients." (PMID 34484156, 2021). "We found an increased expression of IL7R, IL23R (both strains) and IL21R (Eystrup only) by cDC1 and cDC2 subsets, while pDC downregulated IL7R (Eystrup) and upregulated IL21R following infection (both CSFV strains)." (PMID 32733474, 2020). "When analyzed during memory stage after 40 dpi, H-2Kb-SIINFEKL-specific CD8+ T cells were heterogeneously stained for CD44, CD62L, and IL-7R, a phenotype distinct from those of memory cells generated during persistent MHV68 infection." (PMID 30388704, 2018). "IL-7R was expressed highly in PBMC, but IL-15Ra was increased in the lymph node during early infection." (PMID 28096567, 2016). "In the Jak-STAT signalling pathway 12.4% of the genes were differentially expressed at the beginning of infection, including greatly increased expression (>10 fold) of IL6, IL7R, IL11 and IL20." (PMID 23326599, 2013). "We analyzed the expression of IL-7R on GP33 and NP396 tetramer–positive cells at day 8 after infection and found fewer IL-7R+ virus–specific CD8+ T cells in WAS KO mice." (PMID 23141740, 2013). "Compared to patients who did not have any post-operative infection, patients who developed an infection had an increase in monocyte count (p = 0.0037) and CD4+ lymphocyte IL-7R (p < 0.0001) and a decrease in monocyte CD80 (p = 0.0279) and CXCR4 expression (p = 0.0220)." (PMID 38655251, 2024).
infection (continued). "In mouse models of contact hypersensitivity, MCMV infection, and liver injury, ILC1s with high expression of cytokine receptors (IL-7R, CD25, and/or IL-18R) highly proliferate and accumulate in AL, thereby forming the memory and protecting liver from infection and injury." (PMID 37352115, 2023). "In contrast, a significantly higher IL-7R+2W+CD4+ T cell population was observed LdCen−/− infection similar to our previously published results and no change in expression was observed upon LNA treatment (*p < 0.05)." (PMID 31608064, 2019). "Although proliferation of the 2W specific CD4+ T cell population was observed in LNA treated LdWT infection, expression of other markers of early memory such as IL-7R were absent in this population." (PMID 31608064, 2019). "By day 5 post-infection (p.i.), early effector T cells (TeffEarly, CD62LhiCD27+) are detectable, as they have down-regulated IL-7Rα/CD127, but have not yet lost CD62L expression." (PMID 29630679, 2018). "Some analytes were not significantly increased with infection but were significantly reduced by treatment with the anti-IL-7Rα M595: MCP-1, MCP-3, MDC, MIP-1α, MIP3β, GCP-2, IL-18, Tissue Factor, and TPO." (PMID 23057802, 2012). "Expression of the IL-7R α-chain (CD127) on CD8+ T cells during the acute phase of the response is also essential, although not sufficient on its own, for identifying the memory precursors at the acute time of infection." (PMID 23230439, 2012). "A reduction in IL-7R expression was evident only in healthy volunteers (p = 0.0005) and in pre-operative PBMCs isolated from patients with (p = 0.0277) and without (p = 0.0275) subsequent infections." (PMID 38655251, 2024). "Following PBMC stimulation with CD3-CD28 beads, an increase in CD4+ lymphocyte IL-2R expression and a reduction in IL-7R expression were consistent between healthy volunteers, pre-operative and post-operative samples (in patients with and without post- operative infections) (p < 0.05 for all)." (PMID 38655251, 2024). "Further, these antigen-specific CD8+ T cells were maintained in the absence of antigen or infection, a foundational hallmark of memory T cells, through signaling from the homeostatic cytokines, IL-7 and IL-15, via their receptors CD127 (IL-7R) and CD122 (IL-15R)." (PMID 31379821, 2019). "Importantly, the IL-6Rα+IL-7R+ DP population increased with time post infection, whereas effector TFH and non-TFH (IL-7RLO) populations decreased." (PMID 26743592, 2016). "Therefore after infection, Lin−Flt3+CD27+IL-7Rα+ CLP cells fall within the LSKint population." (PMID 24825601, 2014). "In the context of infection, OT1 T cells treated with anti-CD8β downregulated IL-7Rα similarly, but anti-CD8α treated did not." (PMID 30735510, 2019). "Indeed, examination of the gene expression profiles of individual IL-7R-expressing CD8+ T cells at 7 days post-infection has suggested that these cells may not be homogeneous, but instead may be a population comprised of fully mature terminal effector, effector memory, and central memory T cells." (PMID 26765121, 2016). "Furthermore, in control samples, we observed an enrichment of IL7R in the CD8 TCM cluster, while this enrichment was absent in the SIV samples, signifying transcriptional changes in response to infection." (PMID 38060615, 2023). "At 5 days post-infection, Granzyme B+CD4+ T cells up-regulated the adhesion molecule CD44, but expressed neither the co-stimulatory receptor CD27 nor the memory T cell marker CD127 (a subunit of interleukin-7 receptor-α)." (PMID 24367519, 2013).
cancer (117 papers, 2011 to 2026). A tumor composed of atypical neoplastic, often pleomorphic cells that invade other tissues. "The second, F6: inflammatory myofibroblasts (IL11+MMP1+CXCL8+IL7R+), characterizes early human skin wounds, inflammatory diseases with scarring risk and cancer." (PMID 40993240, 2025). "These profiles include the frequent upregulation of the IL7R pathway in type-1 and the enrichment of constitutional cancer predisposition genes and hypermutator phenotypes in type-2 relapses." (PMID 35585141, 2022). "Notably, high levels of expression of α-smooth muscle actin (αSMA) (p = 0.015) and fibroblast activation protein (FAP) (p = 0.048), which are known CAF markers, were also significantly associated with high IL-7R expression in cancer nests." (PMID 36672342, 2023). "Based on the cell line results, we explored whether the expression levels of IL-7 and IL-7Rα are associated with the expression of EMT-related genes in cancer patient samples." (PMID 31061414, 2019). "Due to its dual role in cancer biology, IL-7R has emerged as a potential therapeutic target, prompting efforts to exploit its signaling axis to improve the efficacy and safety of cancer immunotherapies." (PMID 41596598, 2026). "External validation yielded a 4-gene set (GZMK, GZMA, ITGAL, and IL7R); higher gene expression levels predicted better overall survival in The Cancer Genome Atlas cohort (p=0.005)." (PMID 40766148, 2025). "High IL-7R expression in ESCC is associated with poor prognosis, highlighting the potential of IL-7R as a therapeutic target in cancer." (PMID 40313966, 2025). "Immunotherapy with IL-7/IL-7 receptor (IL-7R) has high efficacy in a wide range of malignant tumours and has been demonstrated in animal models and in humans." (PMID 40165301, 2025). "A machine learning model predicts HCC malignancy based on IL7R gene expression, offering valuable insights into treatment options and early cancer management." (PMID 40408005, 2025). "The PI3K‐Akt signaling pathway plays a key role in cell growth, survival, metabolism, and motility, and activation of its related genes (MYD88, IL7R, MYB, CSF1) has been implicated in the initiation and progression of several cancers." (PMID 41328768, 2025). "Deregulation of IL-7/IL-7R signaling can promote cancer development, making it a potential target for therapeutic interventions." (PMID 40313966, 2025). "The L-R pair of IL7-(IL7R + IL2RG) was enriched between cancer cells and immune cells in EEC-II group, which plays a crucial role in the survival and differentiation of lymphocytes via IL7 receptor." (PMID 39112478, 2024). "Furthermore, immunohistochemistry showed that ESCC patients with high IL-7R expression in cancer nests exhibited a trend toward poor prognosis in terms of disease-free survival, and showed significant correlation with increased numbers of infiltrating macrophages and cancer-associated fibroblasts." (PMID 36672342, 2023). "The present study demonstrates that IL-7R expression is upregulated in ESCC cells co-cultured directly with macrophages, and that high IL-7R expression promotes the survival and growth of cancer cells via activation of the Akt and Erk1/2 signaling pathways." (PMID 36672342, 2023).
cancer (continued). "Among the various indications, there is particularly strong interest in the use of IL-7R agonists for treating cancer." (PMID 37874823, 2023). "IL-7 and IL-7R are thought to be critical for regulating the impaired immune system of cancer patients." (PMID 36142322, 2022). "We then summarize the recent progress in the use of IL-7 and IL-7Rα in cancer immunotherapy and discuss their potential for therapeutic applications." (PMID 36142322, 2022). "In this review, we first summarize the roles of IL-7 and IL-7Rα and their downstream signaling pathways in immunity and cancer." (PMID 36142322, 2022). "In this review, we summarize the roles of IL-7, IL-7Rα, and their downstream signaling pathways in immunity and cancer development." (PMID 36142322, 2022). "This review will help in the development of cancer immunotherapy regimens based on IL-7 and IL-7Rα, and will also advance their exploitation as more effective and safe immunotherapy tools." (PMID 36142322, 2022). "RT-qPCR and Western blot results showed that the expressions of AGER, CD69, and IL7R in cancer tissues were significantly lower than those in adjacent tissues." (PMID 36358600, 2022). "These trends are explained by the role of CA19-9 as a cancer-related marker and IL-7R as a cancer-responsive marker." (PMID 35159120, 2022). "BTG2, IL7R, and LAMP3 are significantly downregulated in carcinoma samples, and their high expressions are markedly implicated with more prolonged overall survival, which is consistent with our study." (PMID 35372503, 2022). "IL7R and IL7 are highly expressed in PCa and are associated cancer cell invasion and migration probably by activating the AKT/NF-κB pathway and upregulating MMP-3 and MMP-7 expression." (PMID 32704070, 2020). "Levels of MFNG in this subgroup of tumors also determined the transcriptional status of several Notch target genes such as NKD1, DLX3, EREG, EPHA4, or IL7R, known to be relevant for cancer progression." (PMID 30065304, 2018). "Since the adjuvant effects of IL-7 in enhancing cancer vaccine-induced T-cell responses have recently been demonstrated, we posit that the IL-7Rα+ polyfunctional CD4+ effector cells arising after ACT would be amenable to adjuvant IL-7." (PMID 28939858, 2017). "The situation will deteriorate if the solid tumor expresses a functional IL-7R that promotes cancer progression." (PMID 25955647, 2015). "In each cancer type, we identify combinations of mutated genes that overlap known cancer pathways and also contain potentially novel cancer genes including IL7R and the EphB receptor EPHB3 in STAD, and the scavenger receptor SRCRB4D in GBM." (PMID 26253137, 2015). "However, a positive correlation was observed between the expression of IL-7R in ESCC cancer nests and the infiltration density of CD163- or CD204-positive cells, i.e., TAMs." (PMID 36672342, 2023). "ESCC patients with high IL-7R expression in cancer nests exhibited poor disease-free survival." (PMID 36672342, 2023). "This analysis validated the identification of genes that could be specific to cancer biology, such as IL7R, JUN, NR3C1 in Ba/Sq subtype, NPAS2, FOXQ1, GRHL3 in Luminal samples, or CDKN2C, FOXJ1, MEIS2, FGFR3 in both subtypes." (PMID 36944729, 2023). "In addition, the Cancer Cell Line Encyclopedia (CCLE) IL7R mRNA expression (RNAseq) graph shows a low value." (PMID 35445848, 2022). "However, in the following section, we will detail the therapeutic use of IL-7R pathway antagonists in order to better understand their application in cancer immunotherapy." (PMID 36142322, 2022).